GCNT1P1 (glucosaminyl (N-acetyl) transferase 1 pseudogene 1)
Synonyms: bA189K21.2; formerly GCNT1P
Gene: Processed pseudogene on chromosome 20 (18,420,160 to 18,421,454, reverse strand). Ensembl gene ENSG00000236474.
Diseases named in the same sentence as GCNT1P1 in open-access papers:
GCNT1P1 is named in the same sentence as 1 disease in open-access papers, as found by Europe PMC text mining. Sharing a sentence is not in itself a finding about the gene and the disease. The quoted sentences say what the papers report.
depression (1 paper, 2023). "Finally, the MeanDecreaseGini of GCNT1P1 and AC092745.12 ranked as the top important candidate genes for suicide with depression (AUC = 0.90)." (PMID 36781900, 2023).